IRS2 (insulin receptor substrate 2)
Diseases named in the same sentence as IRS2 in open-access papers (continued):
Sharing a sentence is not in itself a finding about the gene and the disease.
atherosclerosis (11 papers, 2011 to 2025). A disease characterized by the build-up of fatty material and calcium deposition in the arterial wall resulting in partial or complete occlusion of the arterial lumen. "Thirteen miRNAs interacted with the IRS2 mRNA with a free energy of more than −130 kJ/mole, which gives reason to recommend these interactions as diagnostic markers of atherosclerosis." (PMID 33329752, 2020). "Defects in IRS-1 may cause vascular damage and accelerate the progression of atherosclerosis, while IRS-2 delays neointimal formation under IR." (PMID 31258478, 2019). "Studies conducted by us have shown diminished atherosclerosis by lixisenatide and liraglutide in a mouse model of atherosclerosis and IR, the Apoe-/-Irs2+/- mice." (PMID 33440821, 2021). "It was reported that LIGHT enhanced proliferating Ly6Chigh MC and increased atherosclerosis lesion size in ApoE-/-Irs2+/-HL-/- mice." (PMID 34987524, 2021). "In mice, deficiency for the Irs2 gene produces MetS, and partial or total inactivation of Irs2 aggravates atheroma development in the apolipoprotein E-null (apoE−/−) mouse model of atherosclerosis." (PMID 22347652, 2011). "Consistent with the human studies, partial ablation of Irs2 in apoE−/− mice also reduces IRS2/AKT2 and Ras/ERK1/2-dependent signaling, suggesting a causal link between decreased insulin signaling and accelerated atherosclerosis." (PMID 22347652, 2011). "The five key genes related to three pathways included the SNARE interactions in the vesicular transport pathway (SNAP23, VTI1A), the insulin signaling pathway (IRS2, PRKAR1A), and lipid and atherosclerosis (CASP1)." (PMID 38674428, 2024).
metabolic syndrome (11 papers, 2011 to 2025). A cluster of metabolic risk factors for CARDIOVASCULAR DISEASES and TYPE 2 DIABETES MELLITUS. "Accumulating evidence revealed that the inactivation of Akt and the activation of Foxo1 via inhibiting insulin receptor substrate 1 (IRS1) and insulin receptor substrate 2 (IRS2) might act as the underlying mechanism of metabolic syndromes." (PMID 34805099, 2021). "A similar deterioration of adipose tissue function was also described previously in humans, where adipocyte insulin sensitivity was reduced in individuals with metabolic syndrome, with prominent alterations in the lipolysis cascade along with marked downregulation of the IRS2 gene expression." (PMID 41361331, 2025). "In the present study, we speculate that the primary pathway through which GS supplementation improves dyslipidemia in hyperglycemic rats is mainly through enhanced hepatic signaling of insulin depicted by the increased transcriptional activity of Irs1 and Irs2 genes." (PMID 37110174, 2023). "Hence, the present study was undertaken to assess the mechanistic hepatoprotective roles of resveratrol against changes contributed to HFFD-induced metabolic syndrome in rats via evaluation of oxidative/antioxidant molecules, NF-kβ signaling, lipid-related genes (SREBP1-c/PPARα), and IRS-2." (PMID 35990819, 2022).
steatosis (11 papers, 2012 to 2021). Increased lipid within the cytoplasm of cells. "In subjects with steatosis, the expression levels of Irs1 were significantly increased, wheras those of Irs2 were significantly decreased." (PMID 27708333, 2016). "By contrast, these authors found that overexpression of miR-185 resulted in increased insulin receptor substrate-2 (IRS-2) expression, improved insulin sensitivity and reduced steatosis." (PMID 26690233, 2015). "This alteration in insulin sensitivity may have been partially compensated for by increased levels of liver IRS2, protecting from further liver lipid accumulation and steatosis." (PMID 25402228, 2014). "Thus, IRS expression was again assessed in cell culture model of steatosis and increased IRS-2 mRNA levels were found at low insulin concentrations, while our highest insulin condition resulted in increased IRS-1 mRNA." (PMID 22745692, 2012). "Abundant steatosis and inflammatory cells were observed in ALDH2-M, with significantly decreased expression of hepatic genes IRS2, GLUT4, and PGC-1α compared to that in WT-M." (PMID 34439969, 2021). "In the present study, IRS2 expression 5 h post-OGTT was significantly lower in patients with higher lobular inflammation and steatosis grade." (PMID 29749571, 2018). "In addition, 3 genes related to fatty acid oxidation were regulated with insulin receptor substrate 2 (IRS2) being up-regulated whereas carnitine palmitoyltransferase 1 (CPT1) and forkhead box protein A2 (FOXA2) being down-regulated, all of which are mechanistically linked to steatosis." (PMID 25470483, 2014). "In addition, the up-regulation of SREBP-1c as a result of knockdown of IRS-2 leads to an increase in DNL, accumulation of fatty acids in hepatocytes, and finally as a net result exacerbation of steatosis." (PMID 32256346, 2020). "IRS2 mRNA levels were significantly correlated with lobular inflammation and steatosis grade in the glucose-loaded group, but not in the fasting group." (PMID 29749571, 2018).
ovarian carcinoma (10 papers, 2017 to 2024). A malignant neoplasm originating from the surface ovarian epithelium. "Analysis of data sets from GDC TCGA Ovarian Cancer confirmed the amplification of both IRS1 and IRS2 genes, associated with decreased overall survival rates in ovarian cancer patients." (PMID 38272982, 2024). "It is critical to note that the inhibition of IRS1 and IRS2 can have repressive effects on malignant behaviors observed in ovarian cancers and glioblastoma cell proliferation." (PMID 38272982, 2024). "DMC upregulated miR-551a in ovarian cancer cells, which suppressed the insulin receptor substrate 2 gene (IRS2) that acts as an oncogene in many solid tumors." (PMID 39445208, 2024). "A few studies reported that upregulation of DLX5 promotes ovarian cancer cell proliferation by enhancing IRS‐2‐AKT signalling." (PMID 39706818, 2024). "It has been documented that DLX5 upregulation promoted ovarian cancer cells growth by activating IRS-2-AKT signaling." (PMID 34277436, 2021). "We previously reported that DLX5 contributes to AKT signaling in human ovarian cancer cells via direct upregulation of IRS2 transcription." (PMID 28122332, 2017). "Studies have shown that malignant behaviors, including migration and invasion, of ovarian cancers depend on both IRS1 and IRS2 through the activation of the PI3K/AKT pathway." (PMID 38272982, 2024). "In ovarian cancer, DLX5 promotes cell proliferation via upregulation of AKT signaling through the direct transactivation of insulin receptor substrate 2 (IRS2)." (PMID 28122332, 2017). "We previously reported that in human ovarian carcinoma cells, DLX5 transactivates the IRS2 gene via direct binding to the IRS2 promoter, thereby resulting in enhanced AKT signaling." (PMID 28122332, 2017).
colon cancer (9 papers, 2016 to 2025). "In colon cancer point of view, studies have shown that there is a higher risk of CRC (specially IRS2-positive tumors) in men and women who has worked night shifts (for 15 years or more)." (PMID 40356833, 2025). "IRS2 is upregulated in the colon cancer tissues than its surrounding tissues, and the knockdown of IRS2 inhibits the proliferation and clonogenic ability of RKO cells, and increases apoptosis, suggesting that IRS2 may act as an oncogene in colon cancer." (PMID 36017335, 2022). "In this study, we explore the expression and prognostic impact of IRS-1, IRS-2, RUNx3, and SMAD4 in colon cancer." (PMID 36900240, 2023). "In this study, we apply deep learning to digitized pathology images to explore compartment level expression and prognostic impact of IRS-1, IRS-2, RUNX3, and SMAD4 in resected tumors from 452 colon cancer patients." (PMID 36900240, 2023).
heart failure (9 papers, 2015 to 2025). Inability of the heart to pump blood at an adequate rate to meet tissue metabolic requirements. "Together, these data indicate that combined loss of IR/IGF1R or IRS1/IRS2 signaling in the adult heart results in impaired insulin-mediated signaling, heart failure, and increased mortality." (PMID 36125265, 2022). "As the predicted targets of mmu-miR-696, Irs1 is reported to cause heart failure in heart-specific IRS1/IRS2 double-knockout mice." (PMID 29147650, 2017). "They inferred that the myocardial loss of IRS1 and IRS2 caused heart failure." (PMID 35906673, 2022). "IRS2 encodes insulin receptor substrate (IRS) 2; ISR signaling mediates cardiac energy metabolism and heart failure and is associated with CS." (PMID 40264650, 2025). "Double-knock-out studies have shown that cardiac suppression of IRS1 and IRS2 increases apoptosis, results in cardiac dilation and heart failure in neonatal rat ventricular cardiomyocytes." (PMID 37569355, 2023). "Suppressing cardiac IRS-1 and IRS-2 may serve as a fundamental mechanism for induction of heart failure." (PMID 26229969, 2015). "And inhibition of cardiac IRS1 and IRS2 may be a fundamental mechanism for inducing heart failure." (PMID 33547878, 2021). "Both heart-specific IRS1 and IRS2 double-knockout mice and liver-specific IRS1 and IRS2 double-knockout mice prove that cardiac IR promotes heart failure." (PMID 41473239, 2025).
Hypertension (9 papers, 2015 to 2025). The presence of chronic increased pressure in the systemic arterial system. "Insulin signaling via IRS2 continues to stimulate sodium reabsorption in the proximal tubule and causes sodium retention, edema, and hypertension." (PMID 27247938, 2016). "In the PT, IRS2-mediated pathway is preserved and the stimulation of sodium reabsorption by insulin causes sodium retention and possibly subsequent hypertension, whereas the potential impairment of the IRS1-mediated pathway could lead to unsuppressed gluconeogenesis." (PMID 27247938, 2016). "An IRS-2−/− deficient mice model showed progressive neointima formation in response to vessel injury, additionally these mice exhibited increased FFA, triglyceride levels and hypertension." (PMID 37569355, 2023). "Instead, novel correlations between IGF1R, IRS1, IRS2, and insulin appeared with hypertension demonstrating that IGF1 is no longer responsible for activation of intracellular processes through IGF1R." (PMID 31327319, 2019).
insulinoma (9 papers, 2011 to 2026). "In Rat INS1-M3 insulinoma cell line, M3 receptor–mediated activation of Gq leads to increased Irs2 expression via sequential activation of PLC (PLCβ), PKC, and ERK1/237,38." (PMID 33067534, 2020). "al. when insulinoma cells and/or mouse islets were transfected with adenoviruses expressing inducible gain- or loss-of-function of ATF3 and IRS2." (PMID 21541314, 2011). "ER stress in insulinoma cells was shown to impair insulin signaling through activation of ATF3, an ER stress response protein that was implicated in suppression of IRS2 expression." (PMID 21541314, 2011). "Treatments that induced ATF3 activation and IRS2 suppression included induction of apoptosis by combined treatment of insulinoma cells with γ-interferon, TNF-α, or the ER stress activator thapsigargin." (PMID 21541314, 2011). "Additionally, JNK3 silencing in insulinoma cells markedly decreased insulin receptor substrate 2 (IRS2) expression." (PMID 41480766, 2026). "Thus, we analyzed the epigenetic control of insulin receptor substrate 2 (IRS2) expression in the MIN6 mouse insulinoma cell line." (PMID 28886131, 2017). "However, studies in mouse models and cultured insulinoma cells suggest that IGF-I also plays an important role in maintaining β-cell function by mediating IRS-2/PI3K/Akt pathway." (PMID 26599278, 2015). "Overexpression of the SREBP1 gene in insulinoma and islet β-cells also reduced IRS2 protein." (PMID 21541314, 2011). "MicroRNA miR-126 has been found to target IRS-2 as well; in this study the authors found that miR-126 hyperexpression in INS-1β cell line (rat β-cell line derived from insulinoma) induced a reduction of proliferation via downregulation of IRS-1 and IRS-2." (PMID 30469501, 2018). "Copy number alterations involving FOXL2, IRS2, CEBPA and ATRX genes were observed in insulinoma as well as in micro-tumors samples, suggesting that alterations of these genes may promote malignization in the β-cells population." (PMID 34737724, 2021). "In our studied samples of micro-tumors, we have not found alteration in MEN1, but gain status in IRS2, FOXL2 and CEBPA genes was found, suggesting that they can play a role in the development of micro- to macro-tumors, to wit insulinomas, and, accordingly, insulinomatosis." (PMID 34737724, 2021).
melanoma (9 papers, 2015 to 2025). A malignant, usually aggressive tumor composed of atypical, neoplastic melanocytes. "The BRD4/IRS2 inhibitor cocktail (designated hereafter as BRIRi) moderated the malignancy of BMMC lines from four different human melanomas." (PMID 40285526, 2025). "To explore the potential of BRD4, GAB2, and IRS2 as therapeutic targets for melanoma brain metastasis, we evaluated the anti‐melanoma functions of small‐molecule inhibitors of these proteins." (PMID 40285526, 2025). "Here, they found that small‐molecule inhibitors of BRD4 and IRS2, in combination, mimicked the effects of the hemoglobin alpha/beta heterodimer and restricted the malignant phenotype of brain‐metastasizing melanoma cells." (PMID 40285526, 2025). "Two phosphopeptides are currently being tested in melanoma patients, one derived from the insulin receptor substrate 2 (IRS2) and the other from breast cancer antiestrogen resistance 3 (BCAR3) (NCT01846143)." (PMID 36291752, 2022). "We noted higher expression of IGF-receptors, IGF-IR and IGF-IIR and IGF receptor substrates, IRS1 and IRS2 in the epithelial-like melanoma cell lines examined." (PMID 25940796, 2015). "miRNA-7-5p, a novel tumor suppressor in melanoma, acts at least in part through the inhibition of IRS-2 expression and oncogenic Akt signaling." (PMID 26310847, 2015). "However, we showed that the synergistic inhibition of BRD4 by the JQ1 inhibitor and of IRS2 by the NT157 inhibitor exerted a significant anti‐melanoma cell impact." (PMID 40285526, 2025). "In view of the finding that the BRD4/IRS2 inhibitor cocktail downregulates the expression of PD‐L1 in melanoma cells, we propose that these inhibitors may represent an additional approach to reduce the expression of PD‐L1 in cancer cells." (PMID 40285526, 2025). "More specifically, IRS-2 is a target of miR-7-5p found down-regulated in melanoma." (PMID 26029660, 2015). "Previously, the authors identified a heterodimer of the alpha and beta chains of hemoglobin in the brain microenvironment that killed brain‐metastasizing melanoma cells by targeting BRD4 and IRS2 proteins." (PMID 40285526, 2025). "While sites of phosphorylation of the insulin receptor substrate IRS-2 and IGFR2 indicated novel points of regulation in the IGF-1R pathway previously identified to mediate drug resistance in melanoma." (PMID 26029660, 2015). "In melanoma, an analysis of 54 melanoma cell lines by whole genome microarray expression profiling revealed upregulation of IGF-receptors (IGF-IR and IGF-IIR) and IGF-R substrates (IRS1 and IRS2)." (PMID 38395880, 2024).
nonalcoholic fatty liver disease (8 papers, 2015 to 2022). "Consistent with this, Irs2 was also recently implicated in a positive feedback loop driving disease progression and hepatocarcinogenesis in rodent models of nonalcoholic fatty liver disease (NAFLD)." (PMID 30695023, 2019). "Consistent with this notion, Irs1 expression was maintained or rather increased, and Irs2 expression was reduced in the liver biopsy specimens obtained from patients with nonalcoholic fatty liver disease (NAFLD)." (PMID 27708333, 2016). "Moreover, berberine (187.5 mg/kg) enabled the upregulation of insulin receptor substrate 2 mRNA in nonalcoholic fatty liver disease (NAFLD) rat liver." (PMID 36479195, 2022). "The aim of the study was to investigate the relationships between insulin receptor substrate (IRS) 1 (Gly972Arg) and IRS2 (Gly1057Asp) genes with obstructive sleep apnea (OSA) and non-alcoholic fatty liver disease (NAFLD) in Asian Indians." (PMID 34449768, 2021).
glioblastoma (7 papers, 2013 to 2024). The most malignant astrocytic tumor (WHO grade IV). "Persister-like cells and genomic amplifications of IRS2 and other loci are evident in primary glioblastomas and may underlie the inefficacy of targeted therapies in this disease." (PMID 32669109, 2020). "4-phenylbutyric acid, 5-aza-2 ́-deoxycytidine and Olea europaea leaf extract induce apoptosis through upregulation of miR-153 targeting Bcl-2, Mcl-1 and Irs2 in glioblastoma." (PMID 36158686, 2022). "When we examined copy number data from the Cancer Genome Atlas, we found that that the chr13q34 locus including IRS2 was amplified in a subset of primary glioblastomas as well as multiple other primary tumor types." (PMID 32669109, 2020). "It has been shown that reduced expression levels of miRNA-7 correlates with high levels of EGFR and upstream genes involved in Akt pathway (such as IRS-1 and IRS-2), leading to inhibition of migration, invasion and proliferation of glioblastoma cells." (PMID 32592373, 2020). "miR-7 was reported to target EGFR and IRS2 by directly binding to their 3′-UTRs and thereby regulated the pAkt levels in glioblastoma." (PMID 23690991, 2013). "Moreover, miR-153 suppresses the AKT signaling pathway in glioblastoma through reduction in expression of insulin receptor substrate-2 (Irs-2) which acts as a molecular adaptor, mediating influences of insulin and insulin-like growth factor 1 (IGF-1) on cell proliferation." (PMID 36158686, 2022).
neuroblastoma (7 papers, 2012 to 2025). Neuroblastoma (NB) is the most common solid, extracranial childhood tumor. "IRS2 nevertheless is of interest given that ALK uses IRS2 as an effector in neuroblastoma cells, possibly through AKT324 and its signaling control and effects are distinct from IRS140." (PMID 41253884, 2025). "In the IGF1R pathway, we find increased dependency on IGF2BP1, IGF1R, IRS1, and IRS2 in neuroblastoma, Ewing’s sarcoma, pancreas, myeloma, or rhabdomyosarcoma." (PMID 35382456, 2022). "These include correlations between IGF2BP1 and IGF1R (R = 0.48) in Ewing’s sarcoma and between IGF2BP1 and IRS2 dependencies (R = 0.32) in Ewing’s sarcoma and neuroblastoma." (PMID 35382456, 2022). "Neuroblastoma cells are known to exclusively express IRS-2 over IRS-1, consistent with these results." (PMID 24349301, 2013). "Our results demonstrate high levels of phosphopeptides from IGF-1R/IR, as well as its major substrates, IRS-2 and Shc, in MYCN-amplified neuroblastoma cells." (PMID 24349301, 2013). "Specifically, IRS-2, not IRS-1, protects neuroblastoma cells from caspase-mediated apoptosis and promotes tumorigenesis." (PMID 24349301, 2013).
non-small cell lung carcinoma (7 papers, 2019 to 2024). A group of at least three distinct histological types of lung cancer, including non-small cell squamous cell carcinoma, adenocarcinoma, and large cell carcinoma. "For instance, hsa_circ_0000003 is found to promote the progression of non-small cell lung cancer (NSCLC) by regulating the miR-338-3p/insulin receptor substrate 2 (IRS2) axis." (PMID 39290984, 2024). "IRS-1 and IRS-2 expression in normal lung and non-small cell lung cancer were evaluated by immunohistochemistry (IHC)." (PMID 31393907, 2019). "PDK1 is upregulated in non-small cell lung cancer (NSCLC) cells, andPDK1 silencing inhibits the survival of NSCLC cells via the Hippo-YAP/IRS2 pathway." (PMID 39578715, 2024). "miR-7-5p is more of a tumor suppressor that represses oncogenic proteins such as EGFR, IGF1R, IRS-1, IRS-2, RAF1, PIK3CD, mTOR, and PI3K, in various cancers including PDAC, liver, breast, non-small cell lung carcinoma (NSCLC), colorectal (CRC) and ovarian." (PMID 31510100, 2019).